SIRT1 (sirtuin 1)
Diseases named in the same sentence as SIRT1 in open-access papers (continued):
Sharing a sentence is not in itself a finding about the gene and the disease.
Cognitive impairment (continued). "However, when we injected SIRT1 overexpressed virus into the VGULT1 mice’s CA1 region, the expression of SIRT1 and BDNF was significantly increased, synaptic plasticity impairment and neuronal excitability were also recovered, and the cognitive impairment induced by anesthesia/surgery was improved." (PMID 38783169, 2024). "Besides preventing cognitive impairment and neurodegeneration through its antioxidant and anti-inflammatory properties, resveratrol has been shown to be able to enhance mitochondria biogenesis by acting on its main effectors, including PGC-1α, SIRT1, AMPK, ERRs, TERT, TFAM, NRF-1 and NRF-2." (PMID 36237161, 2023). "Therefore, the purpose of this study was to investigate the role of SIRT1/RhoA signaling in the neurotoxicity induced by long-term SEV exposure and the effect and mechanism of RES administered in advance and postoperatively on cognitive impairment in adult rats." (PMID 34247566, 2022). "This study showed that plasma SIRT1 levels were correlated with the nonmotor symptoms of anxiety, depression, EDS, and especially cognitive impairment as well as the total GM volume." (PMID 37718350, 2024). "This study showed that plasma SIRT1 levels were correlated with the nonmotor symptoms of anxiety, depression, EDS and especially cognitive impairment, along with whole-brain GM volume." (PMID 37718350, 2024). "In another study, the levels of SIRT1 were analyzed in brains obtained from subjects with a pre-mortem diagnosis of no-cognitive impairment (NCI), mild cognitive impairment (MCI), mild to moderate AD (mAD), and severe AD (sAD)." (PMID 36978879, 2023).
diabetic nephropathy (165 papers, 2011 to 2026). "This review is aimed at evaluating the association between SIRT1-polymorphisms and diabetic nephropathy susceptibility." (PMID 41624996, 2026). "Association between SIRT1 gene polymorphisms and diabetic nephropathy has been reported and suggested implication of sirtuin‐1 (SIRT1) in the initiation of diabetic nephropathy." (PMID 39474345, 2024). "In various DM-associated complications such as diabetic nephropathy and diabetic osteoporosis in vitro, the high levels of miR-155 have been recognized as a direct suppressor of histone deacetylase SIRT1." (PMID 38396793, 2024). "The anti-inflammatory effects of SIRT1 have been linked to the inhibition of NFkB, which is very important in the changes in diabetic nephropathy." (PMID 39684343, 2024). "Some studies have shown that Sirt1 is closely associated with the pathogenesis of diabetic nephropathy and represents a new potential therapeutic target for diabetic nephropathy." (PMID 33519483, 2020). "In a report about Japanese patients with T2DM, four single nucleotide polymorphisms (SNPs) in SIRT1 that were positively correlated with diabetic nephropathy, and a haplotype containing the SNPs within SIRT1 locus had a stronger association." (PMID 30559718, 2018). "One consequence of hyperglycemia in humans is an increased incidence of nephropathy, and it has recently been shown that polymorphisms within SIRT1 are associated with susceptibility to diabetic nephropathy." (PMID 23880847, 2013). "For instance, a recently published prospective observational study in patients with diabetic kidney disease undergoing lower limb revascularization identified low SIRT1 levels as an independent risk factor for both major adverse cardiovascular events (MACE) and major adverse limb events (MALE)." (PMID 41009597, 2025). "ISL exhibits significant pharmacological effects on the deterioration of diabetic nephropathy by reducing inflammation and oxidative stress associated with its direct binding to Sirtuin 1 (SIRT1), the inhibition of mitogen-activated protein kinase (MAPK), and the induction of Nrf-2 signaling." (PMID 39339760, 2024). "In short, the results of this study provided the first evidence that NMN accumulation, possibly induced by up-regulation of NAMPT and down-regulation of NMNAT1 in diabetic nephropathy, plays a pathogenic role in DN with regulatory effects on NF-κB P65 and Sirt1 signaling pathways." (PMID 35408818, 2022). "It has been reported that the administration of T2 to streptozotocin-induced diabetic rats, eliciting a marked SIRT1 activation-dependent renoprotective action, strongly attenuated the diabetic nephropathy-associated increase in NF-kB p65 subunit acetylation/activation." (PMID 29593557, 2018). "In those reports, mechanisms of Sirt1's antifibrotic effects were explained by suppression of both cyclooxygenase 2 expression and activation of TGFβ-induced Smad3, both of which are recognized as classical pathogenic factors in diabetic nephropathy." (PMID 25126552, 2014). "Although, the mechanism by which the SIRT1 polymorphism contributes to conferring susceptibility to diabetic nephropathy remains to be elucidated, combining the present finding with a previous report, SIRT1 and FOXO1 may be considered a good new candidate gene for diabetic nephropathy." (PMID 28860538, 2017). "Metformin enhances autophagy and inhibits abnormal cell proliferation through the AMPK/SIRT1-FoxO1 pathway, thereby mitigating oxidative stress in diabetic nephropathy." (PMID 41480421, 2025). "In vitro, the lncRNA TUG1/miR-29c-3p/SIRT1 axis regulates endoplasmic reticulum stress-mediated injury in renal epithelial cells in a diabetic nephropathy model." (PMID 41295241, 2025). "The significance of SIRT1 in podocyte protection and the potential of BF175 as a novel SIRT1 agonist in the treatment of diabetic kidney disease." (PMID 40862124, 2025).
diabetic nephropathy (continued). "Specifically, a study conducted on a group of 140 patients with diabetic nephropathy provides supporting evidence, as it demonstrated that SIRT1 expression in the serum decreases in parallel with Kt/V, a standard indicator of dialysis adequacy." (PMID 41009597, 2025). "The apoptosis mechanism induced by mitochondrial damage mediated by Sirt1 also participates in the pathological process of diabetes nephropathy and can improve symptoms or delay disease progression by regulating its pathway." (PMID 40291778, 2025). "Although patients with diabetic kidney disease tend to exhibit lower SIRT1 levels, findings on the correlation between SIRT1 and the severity of kidney damage remain inconsistent." (PMID 41009597, 2025). "Our team has revealed for the first time that the WYJDTLF can improve lipid metabolism abnormalities in db/db mice and alleviate diabetic kidney disease-induced renal pathological damage by inhibiting the JAML/SIRT1 signalling pathway." (PMID 40837398, 2025). "The results of this study confirmed that the T allele of the SIRT1 rs3758391 is a strong risk factor for T2DM and diabetic nephropathy among a population from southwest Iran." (PMID 39474345, 2024). "Sirt1 has protective effects on various kidney diseases, such as acute renal injury, diabetes nephropathy, and CAD." (PMID 39687299, 2024). "In diabetic kidney disease, oxidative stress induces SIRT1 ubiquitination, facilitating its degradation." (PMID 39911234, 2024). "In diabetic kidney disease (DKD), endothelial SIRT1 dysfunction leads to peritubular capillary loss following kidney injury." (PMID 39598406, 2024). "Exenatide mediates attenuation of diabetic nephropathy by SIRT1-dependent down-regulation of thioredoxin-interacting protein H3K9ac acetylation and reduces the recruitment of spliced X-box binding protein 1 to the Txnip promoter." (PMID 39598478, 2024). "Arctigenin was found to inhibit nuclear factor-κB (NF-κB) phosphorylation, a primary proinflammatory pathway activated in human diabetic kidney diseased kidneys, through activation of Sirtuin 1 (Sirt1)." (PMID 38611326, 2024). "S‐sulfhydration of SIRT1 and Kelch‐like ECH‐associated protein 1 (KEAP1) plays a significant role in diabetic complications, particularly in the context of diabetic nephropathy, a critical complication of DM." (PMID 39355507, 2024). "This anti-apoptotic mechanism is mediated through the activation of AMP-activated protein kinase (AMPK) and subsequent regulation of the AMPK/SIRT1-FoxO1 pathway, which plays a crucial role in autophagy and cellular homeostasis in diabetic nephropathy." (PMID 39144694, 2024). "miR-155 has been identified as a direct repressor of the histone deacetylase Sirtuin 1 (SIRT1) in various pathologies including diabetic nephropathy and diabetic osteoporosis in vitro." (PMID 38396793, 2024). "LncRNA 1700020I14Rik reduces cell proliferation and fibrosis via the miR-34a-5p/Sirt1/HIF-1α signaling pathway in diabetic nephropathy." (PMID 37988356, 2023). "Crocin is reported to increase Sirt1 expression in diverse experimental models, including depression model, diabetic nephropathy model, and myocardial ischemia/reperfusion model." (PMID 37724538, 2023). "Isoflavonoid formononetin was reported to attenuate renal tubular injury by upregulating Sirt1/PGC-1α pathway in diabetic nephropathy." (PMID 37650573, 2023). "The expression level of SIRT1 protein is closely related to the development of diabetic nephropathy as well as hyperglycemic status." (PMID 37505163, 2023). "miR‐133b was also proven to inhibit TGF‐β1‐induced EMT and renal fibrosis by upregulating SIRT1 in diabetic nephropathy." (PMID 36846934, 2023).
diabetic nephropathy (continued). "Recent study have demonstrated that enhancing SIRT1 antagonizes oxidative stress in the pathogenesis of diabetic kidney disease and that AMPK is an critical mediator that regulates SIRT1-mediated oxidative stress reduction." (PMID 37723077, 2023). "In our previous study, we find that both mRNA and protein levels of Sirt1 are reduced in glomeruli of patients with diabetic kidney disease (DKD) as assessed by qPCR and immunostaining." (PMID 35795148, 2022). "LncRNA AK044604 (regulator of insulin sensitivity and autophagy, Risa) and autophagy-related factors Sirt1 and GSK3β play important roles in diabetic nephropathy (DN)." (PMID 35614465, 2022). "GDC ameliorated the development of diabetic nephropathy by reduction of lipids accumulation in the kidney via SIRT1/AMPK/HNF4A pathway." (PMID 35480869, 2022). "The overexpression of connexin 43 also improves renal function in diabetic nephropathy by upregulating Sirt1 expression and enhancing Sirt1-dependent deacetylation and inactivation of HIF-1α." (PMID 35874275, 2022). "LncRNA GAS5 suppressed fibrosis and cell proliferation through attenuating miR-221 and upregulating SIRT1 expression in diabetic nephropathy." (PMID 36313695, 2022). "For diabetic nephropathy, PT-specific Sirt1 transgenic mice showed prevention of albuminuria and glomerular changes in streptozotocin (STZ)-treated and db/db mice while PT-specific Sirt1 KO mice showed worsening of the same parameters in STZ-treated mice." (PMID 36611814, 2022). "The renal protective effects of Sirt1 have been described in many kidney diseases such as diabetic kidney disease and HIV-related kidney disease." (PMID 35795148, 2022). "P2Y2R can lead to AKT and SIRT1/FOXO3a-mediation autophagic function disorder, which in turn promotes the development of diabetic nephropathy." (PMID 35493297, 2022). "Our previous study confirmed that Yishen capsule promotes podocyte autophagy through regulating SIRT1/NF-κB signaling pathway to improve diabetic nephropathy." (PMID 36094934, 2022). "Numerous studies have shown that SIRT1 is expressed in the kidney, and it protects the kidney from both chronic and acute kidney diseases, such as acute kidney injury, diabetic nephropathy, and renal fibrosis." (PMID 35386302, 2022). "Lastly, AMPK-activating resveratrol, a polyphenol that also activates sirtuin 1 (SIRT1), was used to reverse diabetic nephropathy and prevent lipid-induced nephrotoxicity in db/db mice." (PMID 36106024, 2022). "A recent publication in JASN reported that short-term treatment with NMN ameliorated the renal injury phenotype and survival of diabetic nephropathy by upregulating SIRT1 expression." (PMID 36052119, 2022). "Attenuated renal function and glomerulosclerosis has been demonstrated in rats with diabetic nephropathy via activation of SIRT1 through RSV treatment." (PMID 34685718, 2021). "Previous study has found that OIP5-AS1 regulates HIF-1α expression in diabetic nephropathy via miR-34a-5p/Sirt1 axis." (PMID 34513821, 2021). "miR-34a-5p directly suppressed SIRT1 in HG-stimulated human proximal tubule cells in the tubulointerstitial fibrosis of diabetic nephropathy." (PMID 35052597, 2021). "Inhibiting endogenous NAMPT alleviates diabetic nephropathy inflammatory-fibrosis by regulating NF-κB p65 and Sirt1 pathways." (PMID 32618342, 2020).
diabetic nephropathy (continued). "It is worthy of note that the implication and importance of SIRT1 in kidney-related diseases, such as diabetic nephropathy, acute and chronic kidney disease or lupus nephritis can be explained by its involvement in numerous pathways regulation." (PMID 32887498, 2020). "SIRT1 is known to protect pathogenesis of diabetic nephropathy (DN) along with regulation of mitochondrial biogenesis." (PMID 32050658, 2020). "Long noncoding RNA GAS5 was proved to limit cell proliferation and fibrosis by sponging miR-221 and regulating SIRT1 levels in diabetic nephropathy." (PMID 32528555, 2020). "SGLT2 inhibitors lead to enhanced AMPK/SIRT1 signaling thus increasing authophagy and tubuloglomerular feedback both underpinning the SGLUTi protective effects on diabetic kidney disease." (PMID 32549243, 2020). "Other studies suggest that anthocyanin and resveratrol reduce albuminuria, glomerulosclerosis, and tubulointerstitial fibrosis in diabetic nephropathy through the activation of AMPK/SIRT1 signaling." (PMID 32050658, 2020). "The activation of AMPK preserve podocyte and renal tubular structure and glomerular function, whilst the overexpression of SIRT1 improves glomerular and renal tubulointerstitial injury in experimental models of diabetic nephropathy." (PMID 32549243, 2020). "Diabetic nephropathy is one of the leading causes of CKD, in which the role of SIRT1 has been more intensively studied." (PMID 31637223, 2019). "In conclusion, our study demonstrated the contribution of the PRR to the reduction of mitochondrial biogenesis and function in diabetic kidney disease via decreasing AMPK/SIRT-1/ PGC-1α signaling pathway." (PMID 31800607, 2019). "The autophagy activity is regulated by SIRT-1 whose expression is inversely correlated with the pathology and progression of diabetic kidney disease." (PMID 30405076, 2018). "Wen and collaborators have also demonstrated the beneficial effects of RVT in ameliorating diabetic nephropathy through activation of SIRT1." (PMID 29104258, 2017). "RAGE is critical in Sirt1 inhibition through the ubiquitin-proteasome pathway in diabetic nephropathy." (PMID 29209448, 2017). "The findings of this study indicate that SIRT1 is a protective molecule in diabetic nephropathy and retinopathy." (PMID 25753689, 2015). "In this paper, we would like to review the protective functions of sirtuins and the role of SIRT1 in the onset of kidney disease based on previous studies, including diabetic nephropathy, acute renal injury, chronic kidney disease as well as lupus nephritis." (PMID 25386563, 2014). "Collectively, these results strongly support Sirt1 activation being considered as a new therapy to improve the prognosis of diabetic nephropathy." (PMID 25126552, 2014). "Actually, activation of SIRT1 by T2 ameliorates diabetic nephropathy in rats, and SIRT1-activation by the specific agonist SRT1720 in mice and by T2 in rats has been shown to result in indirect activation of AMPK in the longer term." (PMID 23880847, 2013). "Although direct renoprotective effects of Sirt1 in diabetic nephropathy have yet to be elucidated, Sirt1 has shown renoprotective activity in aging kidneys and fibrotic kidney diseases." (PMID 22028701, 2012). "Pharmacologic intervention to normalize Sirt1 expression or prevent acetylation of Foxo4 should be explored as potential approaches to improve the outcome of diabetic kidney disease." (PMID 21858169, 2011). "Sirt1 is a Cdk5 substrate In an HG environment, Sirt1 regulates oxidative stress, reduces inflammation and apoptosis in renal cells, and improves renal interstitial fibrosis in diabetic nephropathy." (PMID 41181709, 2025).